WTAP (WT1 associated protein)
Diseases named in the same sentence as WTAP in open-access papers (continued):
Sharing a sentence is not in itself a finding about the gene and the disease.
tumor (continued). "As expected, compared to the adjacent normal tissues, EC tumor tissues had over 2-fold expression of WTAP mRNA." (PMID 34081626, 2021). "The knockdown of WTAP significantly delayed the tumor growth and dramatically decreased the tumor volume." (PMID 33937023, 2021). "To this end, we studied the expression of WTAP in GC tissue, the effect of WTAP expression on tumour immune cell infiltration and patient prognosis, and then explored the mechanism by weighted gene co‐expression network analysis (WGCNA)." (PMID 32176425, 2020). "Moreover, other recent studies in other tumor entities also demonstrate WTAP itself as a useful prognostic marker." (PMID 40699665, 2025). "To confirm the role of WTAP, EGR1, and PTEN in tumor growth in vivo, we constructed xenograft tumor models in nude mice by subcutaneous injection of overexpression of WTAP, EGR1, and PTEN in ECCs and ECSCs, respectively, or combined overexpression of WTAP + EGR1 or EGR1 + PTEN." (PMID 39044249, 2024). "Therefore, it is essential to identify new molecules to target WTAP or its molecular partners to counteract tumor progression." (PMID 38862471, 2024). "Moreover, the upregulation of WTAP promoted tumor proliferation and metastasis, usually indicating poor prognosis, and was an independent prognostic risk factor for cancer." (PMID 37297015, 2023). "Moreover, several studies have confirmed the close association of m6A regulatory factors ALKBH5, WTAP, and ELAVL1 with the pathological process of tumor invasion and metastasis." (PMID 37684273, 2023). "Moreover, WTAP overexpression promotes osteosarcoma tumorigenesis by suppressing homeobox-containing 1 (HMBOX1) expression and is correlated with tumour-associated T lymphocyte infiltration in gastric cancer, indicating a poor prognosis." (PMID 35143566, 2022). "Therefore, to comprehensively explain the relationships of WTAP and immune cells infiltration, we further analyzed the correlations of WTAP expression and gene markers in normal and tumor tissues of LIHC and ESCA in GEPIA." (PMID 36171885, 2022). "While METTL14, WTAP, METTL3, ALKBH5, and YTHDC2 had lower expression in high risk group, indicating that they might be tumor suppressor." (PMID 35077391, 2022). "Consistent with this, previous studies have identified that WTAP can function as both an oncogene and tumour suppressor dependent on cancer type and it may be that WTAP functions differently in varying stages of PCa." (PMID 36733939, 2022). "Additionally, WTAP depletion significantly suppressed xenograft-tumor growth and enhanced sensitivity and apoptosis of tumor cells in vivo." (PMID 33680959, 2021). "Moreover, the WTAP expression was positively correlated with the advanced stages of Tumor-Node-Metastasis (TNM) and high rates of vascular invasion." (PMID 33937023, 2021). "In supporting of the contribution of WATP in conferring chemoresistance, our ECA-109 xenograft mice with reduced tumor burden all displayed markedly decreased expressions of WTAP mRNAs and proteins, and WTAP knockout in tumors significantly attenuated the resistance to DDP treatment." (PMID 34081626, 2021). "In glioblastoma, WTAP was found to be overexpressed and to regulate tumor invasion and migration." (PMID 34956201, 2021). "However, it seems contradictory for METTL3, METTL14, and WTAP, the three components of the methyltransferase complex, to exhibit different effects on tumor cells." (PMID 33314339, 2021). "Notably, WTAP KO and IGF2BPs KO suppressed tumor growth in both subcutaneous and orthotopic transplantation models in immunodeficient mice." (PMID 34326314, 2021). "WTAP as a single factor was further analyzed in the tumor group and normal group, the relationship between high and low WTAP expression and clinicopathological factors, and whether it can be treated as an independent prognostic factor." (PMID 34291082, 2021).
tumor (continued). "However, after adjusted to age, molecular classification, grade, tumor size, lymph node status, endocrine treated, and chemotherapy treated, only YTHDC1, FMR1, IGF2BP1 and WTAP showed a significant association." (PMID 34141492, 2021). "On the contrary, METTL14, ZC3H13, FTO, and WTAP are low-expressed in tumor tissues." (PMID 32258108, 2020). "We found that the copy number loss of ZC3H13, FTO, YTHDC2, WTAP and ALKBH5 decreased the protein expression in tumor samples, and meanwhile, patients with amplification of IGF2BP3, HNRNPA2B1 and IGF2BP2 presented higher expression level of these three proteins than normal tissues." (PMID 32710725, 2020). "Other “writers” (METTL16, WTAP, KIAA1429, RBM15) are likewise overexpressed, suggesting a broader activation of the m6A writing machinery, whereas METTL14 loss correlates with poor differentiation and aggressive behavior suggesting a tumor-suppressive role similar to that seen in gastric cancer." (PMID 41228380, 2025). "The results indicate that high expression of WTAP was associated with a variety of classical cancer-promoting pathways including the MAPK signaling pathway and PI3K-Akt signaling pathway, which had been proved to be the ROS-related mechanism of promoting tumor growth." (PMID 38535989, 2024). "According to the role of MALAT1 in worsening tumor progression, we have shown that WTAP expression levels significantly correlate with the worst clinical outcome shortening the overall survival and disease-free survival, identifying WTAP as a new effector of MALAT1." (PMID 38862471, 2024). "In addition, WTAP expression was closely related to the tumor stage of HCC." (PMID 37231451, 2023). "Therefore, WTAP has high clinical therapeutic promise in tumor therapy." (PMID 36139062, 2022). "In addition, WTAP expression was found to be significantly higher in high-grade plasmacytoid OC than in normal cancer tissues, and it could significantly modulate tumor progression." (PMID 35733918, 2022). "In addition, WTAP can directly regulate the formation of tumor drug resistance." (PMID 36139062, 2022). "Thus, WTAP may play a pathogenic role in HCC progression by acting on both tumor cells and tumor-infiltrating immune cells." (PMID 35480109, 2022). "WTAP could promote tumor metastasis via stabilizing Fak mRNA and would result in a poor prognosis." (PMID 35046996, 2021). "In selected tumor entities, two important new central target structures, PUS7 and WTAP, were identified that directly control essential points for proliferation, which was impressively supported by annotation clustering." (PMID 40699665, 2025). "In this study, the expressions of WTAP, METTL14, YTHDF3 were inhibited in tumor tissues, the decrease of WTAP levels was most apparent." (PMID 39744575, 2025). "Taken together, these studies reveal that the interplay between METTL3, METTL14 and WTAP fine-tunes m6A methylation activity, influencing the balance between CSC maintenance and differentiation across tumor types." (PMID 41228380, 2025). "These experimental findings provide compelling evidence of the critical roles of WTAP, EGR1, and PTEN in regulating tumor growth and maintaining stem cell-like characteristics in EC." (PMID 39044249, 2024). "Specifically, the m6A writers METTL3, WTAP, and RBM15B and the m6A readers YTHDF1 and HNRNAPA2B1 showed significant upregulation in the high PCa tumor grades compared to the low tumor grades and adjacent normal tissues." (PMID 38610981, 2024). "Decreased expression of WTAP has been shown to disrupt the transforming growth factor β (TGF-β) signaling pathway, inhibit cell cycle arrest, and promote tumor proliferation." (PMID 39033180, 2024). "IGF2BP1, HNRNPA2B1, FTO, WTAP promote the EC progression, but METTL3, METTL14, YTHDF2 work as tumor suppressors in EC." (PMID 39582531, 2024).
tumor (continued). "First, we studied the mRNA levels of the m6A regulatory factors between TCGA-derived tumors and normal samples, which showed greater expressions in the tumor samples, including METL3 and WTAP (p<0.01)." (PMID 37244287, 2023). "On the other hand, WTAP and METTL3 are abundantly expressed in HCC and are necessary for tumor cell proliferation." (PMID 37777158, 2023). "To further validate the results, we obtained 60 paired tumor tissues and adjacent normal tissues of ESCC, and qRT-PCR was used to determine the expression pattern of METTL3, METTL14, WTAP, FTO, ALKBH5, YTHDF1 and YTHDF2." (PMID 35399719, 2022). "Immunohistochemistry confirmed the high expression of WTAP, DNMT1, and DNMT3B in tumor tissue, but the low expression of TRMT6." (PMID 36203569, 2022). "Particularly, m6A writers showed high up-regulated expression in tumor samples, such as METTL3, RBM15, RBM15B and WTAP." (PMID 35847857, 2022). "Given that m6A writers are important for cancer progression, usually as a tumor promoter during tumor progression, this study explored the expression of m6A writers, including METTL3, METTL14, and WTAP, in tumor and adjacent normal tissues." (PMID 35778697, 2022). "At the transcriptional and translational levels, WTAP, METTL3, and METTL14 were highly expressed in hypodifferentiated tumor tissues, and the total m6A expression level was generally higher in general hypodifferentiated tissues." (PMID 36139062, 2022). "High WTAP expression was identified in 54.9% (56/102) of grade III tumor tissue, in 30.7% (70/228) of grade II tumor tissue and in 23.5% (4/17) of grade I tumor tissue (P < 0.001)." (PMID 35046505, 2022). "It appeared that IGF2BP1/3, ELAVL1, HNRNPA2B1, HNRNPC, KIAA1429, RBM15, LRPPRC, FMR1, YTHDF1/2 are highly expressed in the tumor while FTO, METTL14/16, WTAP, YTHDC1 and ZC3H13 are down-regulated." (PMID 35095993, 2021). "The tumor cells exhibited a significant increase in the expression of WTAP, YTHDF2, and YTHDF3, but a reduction in the expression of FTO and ALKBH5 compared to the normal epithelial cells in the para-tumor samples." (PMID 34733841, 2021). "Meanwhile, we found that the expressions of METTL3, METTL14, WTAP, and YTHDF1-3 proteins were significantly lower in the stroma cells than that in the tumor cells." (PMID 34733841, 2021). "IHC staining analysis of m6A “writer” suggested that WTAP, KIAA1429 and RBM15/15B expression were upregulated in GC tumor tissues compared with that in normal gastric tissues at protein level, which was consistent with the expression pattern of genes." (PMID 32226518, 2020). "We examined the expression of 17 m6A-related genes in GEO database, and found that WTAP, RBM15, YTHDF1, and YTHDF2 were differently expressed in tumor tissue compared with control tissue." (PMID 32814762, 2020). "Comparisons between adjacent normal and tumor samples identified seven down-regulated (METTL14, WTAP, YTHDC1, YTHDC2, ALKBH5, FTO, and YTHDF2) and one up-regulated (YTHDF1) regulators." (PMID 32500031, 2020). "Five m6A-related genes (ZC3H13, METTL14, YTHDF2, YTHDF3 and HNRNPA2B1) showed significantly downregulated in tumor tissue, while seven regulators (YTHDC2, FTO, WTAP, METTL3, ALKBH5, RBM15 and KIAA1429) was remarkably upregulated in ccRCC." (PMID 32419773, 2020). "Thus, WTAP may participate in tumor progression functioning as an m6A mediator." (PMID 31438961, 2019). "WTAP promoted DLBCL cell proliferation and improved the ability to confront apoptosis, while knockdown of WTAP in DLBCL cell lines allowed a significant higher apoptosis rate after treatment with Etoposide, an anti-tumor drug." (PMID 30143009, 2018). "Additionally, WTAP upregulates ATG5 post-transcriptionally in an m6A-YTHDC2-dependent manner, promoting ferroptosis in HCC and inhibiting tumor progression." (PMID 40271153, 2025). "Furthermore, comparative analyses also identified further putative target mRNAs of importance for tumor biology of PUS7 and WTAP." (PMID 40699665, 2025).
tumor (continued). "Moreover, the overall m6A level and its related METTL3, METTL14, and WTAP protein levels, as well as cytoplasmic MALAT1-exporting IGF2BP3 and its distribution in xenograft tumor tissues, were increased in the HBx group." (PMID 40860202, 2025). "Thus, we first examined the expression levels of METTL3, METTL14, WTAP, RBM15, FTO, and ALKBH5 transcripts in tumor samples and corresponding normal samples using the GEPIA database." (PMID 38665783, 2024). "Considering the importance of ROS in malignant tumors, we speculate that WTAP is involved in the regulation of ROS in GBM and may affect the malignant progression of GBM and the change of its tumor microenvironment." (PMID 38535989, 2024). "Previous studies have found that expression of METTL3 and WTAP are regulated by androgen in PC cell lines, as well as increased expression of METTL3 plays a pro-tumor role in PC, while METTL3 silencing resulted in upregulation of AR, together with 134 AR-regulated genes." (PMID 38042806, 2023). "Because we surprisingly found that both “writers” (METTL3, METTL14 and WTAP) and “erasers” (ALKBH5 and FTO) could abnormally overexpressed and exert oncogenic functions or downregulated and play tumour suppressor roles in urologic tumours." (PMID 37284313, 2023). "Besides, CAPRIN1 knockdown inhibits ESCC cell proliferation and tumour growth and decreased the expression of METTL3 and WTAP." (PMID 36855123, 2023). "Immunohistochemistry analysis showed that the expression of WTAP, DNMT1, and DNMT3B in tumor tissues was significantly higher than that in paracancerous tissues, whereas the expression of TRMT6 was low in tumor tissues." (PMID 36203569, 2022). "In addition, B-cell lymphoma 6 (BCL6), a transcriptional repressor, a vital tumor protein in DLBCL that has been evaluated as a therapeutic target, forms a complex with Hsp90 and WTAP." (PMID 36139062, 2022). "Also, the expression levels of YTHDC2, WTAP, and FTO were markedly lower in tumor tissues (p < 0.05)." (PMID 34277622, 2021). "In conclusion, the m6A methyltransferases METTL3, METTL14, WTAP, KIAA1429, and METTL4 are dysregulated in ccRCC and might act as tumor suppressor genes." (PMID 35474700, 2021). "A comparison of all results showed that the HNRNPC, WTAP, YTHDF2, and YTHDF1 were up-regulated in tumor samples and might influence the tumorigenesis of GBM." (PMID 33134160, 2020). "Similarly, WTAP expression levels were significantly increased and showed a negative correlation with miR-127-5p levels in tumor tissues of HCC patients." (PMID 36932387, 2023). "Moreover, in LIHC, WTAP expression shows a negative correlation with tumor purity which indicates the multifaceted function of WTAP in tumor development." (PMID 36171885, 2022). "Moreover, WTAP expression did not appear to be related to other clinical parameters such as sex, age, tumor size, T stage, and TNM stage." (PMID 35480109, 2022). "Finally, 8 genes related to anti-tumor immunity were obtained, which were APOL3, CCL5, CD8A, CD8B, CXCL9, GZMA, GZMK and PRF1.We found that the m6A regulatory factors YTHDC1, YTHDC2, and WTAP were positively correlated with m6A, while IGF2BP3 was negatively correlated." (PMID 34737950, 2021). "Most increased regulators in tumor cases compared to normal cases were YTHDF2 (p < 0.001), FTO (p < 0.001), YTHDC1 (p < 0.001), YTHDC2 (p < 0.001), YTHDF1 (p < 0.001), KIAA1429 (p < 0.001), METTL3 (p < 0.010), WTAP (p < 0.001), RBM15 (p < 0.001), HNRNPC (p < 0.001), and ALKBH5 (p = 0.001)." (PMID 32733931, 2020). "In addition, among those differential expression regulators, the expressions of WTAP and FTO exhibited significantly sustained elevated and decreased with the progression of CRC, respectively, suggesting enhanced m6A RNA methylation with the increasing tumor grade." (PMID 32500031, 2020). "METTL3, METTL14, WTAP and CBLL1 were expressed at the protein level in both non-malignant prostate and tumour tissue." (PMID 36733939, 2022).
tumor (continued). "As well, reduced level of the m6A members METTL3, METTL14, WTAP and FTO but not their mutation and overexpression was tightly associated with cancer progression and poor survival, and these could be developed as novel prognostic markers to predict tumor recurrence." (PMID 30953473, 2019).
cancer (86 papers, 2010 to 2025). A tumor composed of atypical neoplastic, often pleomorphic cells that invade other tissues. "The high expression of WTAP is closely related to the poor prognosis caused by many malignant tumors such as NSCLC,CRC." (PMID 41256854, 2025). "Research has also identified WTAP’s association with a spectrum of immune cells in the tumor microenvironment, including cancer-related fibroblasts, myeloid dendritic cells, and various T cells." (PMID 38148841, 2023). "WTAP is strongly expressed and associated to an unfavorable prognosis in cancers such as osteosarcoma, glioma, and acute myeloid leukemia." (PMID 35480109, 2022). "There is an increasing body of literature that recognizes the expression level of WTAP is associated with progression and prognosis of cancers." (PMID 36171885, 2022). "In this article, we demonstrate that WTAP is closely associated with cancer, providing new potential biomarkers and therapeutic targets for pan-cancer treatment and prognosis assessment." (PMID 36171885, 2022). "It has been shown that Wilms' tumor 1-associating protein (WTAP) is frequently upregulated in various cancers." (PMID 33937023, 2021). "pointed out that the overexpression of Wilms tumor 1 associated protein (WTAP) was significantly correlated with poor cancer prognosis, as it facilitated the EMT in GC cells by modulating TGF-β expression and stability of mRNA, consequently leading to multiple chemotherapy resistance and metastasis." (PMID 40052129, 2025). "In TNBC, WTAP has been linked to cancer progression, glycolysis, and drug resistance." (PMID 38862471, 2024). "Additionally, association analysis of the PCa-associated risk loci in the cancer genome atlas program (TCGA) data unveiled genetic variations near the WTAP, HNRNPA2B1, and FTO genes as significant expression quantitative trait loci." (PMID 38610981, 2024). "However, a number of recent studies have also shown that WTAP was act as an oncogene and was associated with malignant tumors closely." (PMID 32742465, 2020). "Recent reports have shown that METTL3 and WTAP, two components of the functional methyltransferase complex, can influence cell proliferation in different cancer types through the AKT signaling pathway." (PMID 38649363, 2024). "WTAP is widely expressed in a variety of human tissues and its expression is dysregulated in cancer through different mechanisms." (PMID 38862471, 2024). "WTAP has been found to be expressed abnormally in a large number of cancers and affects cancer progression and prognosis." (PMID 37297015, 2023). "In this review, we will focus on the latest advances in the biological functions of WTAP in cancer, and explore the prospects of its application in clinical diagnosis and therapy." (PMID 37297015, 2023). "Due to the crucial function of WTAP in cancer progression, it is urgent to design and develop effective WTAP inhibitors." (PMID 37297015, 2023). "In most cancers studied, WTAP is almost an oncogene, closely related to the occurrence and progression of tumors." (PMID 37297015, 2023). "WTAP is widely expressed in a variety of human tissues and is dysregulated in cancer expression through different mechanisms." (PMID 36139062, 2022). "Several studies have reported upregulation of WTAP in malignant tumors and the finding that WTAP acts as an oncogene, promoting cancer occurrence and development." (PMID 35143566, 2022). "WTAP can also promote invasion and metastasis of cancer cells by regulating epidermal growth factor receptor (EGFR) or mRNA expression." (PMID 36171885, 2022). "In patient tissue samples, immunohistochemistry results and western blot results have shown that WTAP is highly expressed in dozens of cancers." (PMID 36207306, 2022). "This study indicates WTAP expression level is correlated with the prognosis of various cancer which is possibly resulted from infiltration of immune cells." (PMID 36171885, 2022).